ESR1 (estrogen receptor 1)
Diseases named in the same sentence as ESR1 in open-access papers (continued):
Sharing a sentence is not in itself a finding about the gene and the disease.
lung carcinoma (142 papers, 1993 to 2026). "Molecular docking analysis was conducted to evaluate the binding affinities of the top 10 MQLEO-derived compounds against four lung cancer-associated targets (ESR1, CASP3, PPARG, and PTGS2)." (PMID 40573169, 2025). "Examples include its role in the molecular characterization of lung cancer and the detection of estrogen receptor alpha (ESR1) mutations in patients with hormone receptor (HR) positive/human epidermal growth factor receptor 2 (HER2) -negative metastatic breast cancer." (PMID 40255897, 2025). "Furthermore, is has been shown that estrogen-related SNPs influence cancer prognosis; a variant of the ESR1-07 SNP was associated with increased tumor ERα mRNA levels and poorer lung cancer prognosis." (PMID 35565393, 2022). "Accordingly, we speculated that the mechanisms of ADI on treating lung cancer were associated with the regulation of ESR1, NCOA1, RXRA, and RELA." (PMID 33506873, 2021). "Furthermore, the strong inverse correlation of SNAI2/SLUG with ESR1 underlines and validates the prognostic relevance of ESR1 in lung cancer." (PMID 25928859, 2015). "ESR1 (estrogen receptor alpha), a nuclear hormone receptor, has emerged as a critical mediator in lung cancer progression, particularly in non-small cell lung cancer (NSCLC)." (PMID 40573169, 2025). "It has been suggested that higher ESR1 expression is correlated with worse OS in lung cancer patients." (PMID 38180107, 2023). "Despite a higher positive correlation (Pearson correlation coefficient R ≈ 0.84), we determined several known lung cancer-associated genes with high RS and low |log2FC|, such as TRIM28, APP, ESR1, MYC, and EGFR." (PMID 36229842, 2022). "Increased expression of ESR1 is related to enhanced innate immunity, which inhibits the metastasis of lung cancer." (PMID 34784845, 2021). "These all indicated ESR1 as a prognostic factor in lung cancer and as a potential target of hormone therapy." (PMID 23762832, 2013). "ESR1 has been proposed to play a regulatory role in liver, prostate, endometrial, and lung cancer." (PMID 41048345, 2025). "Assessment of p16 and ESR1 methylation in blood facilitates early diagnosis of lung cancer, and these methylation genes may be biomarkers for early lung cancer." (PMID 36726839, 2023). "It has been shown that ESR1 signaling plays a biological role in both epithelial and mesenchymal cells in the lung and that ESR1 may promote lung cancer by acting directly on precancerous or tumor cells or indirectly on lung fibroblasts." (PMID 36726839, 2023). "Furthermore, based on our interactome, ESR1 appears to be central and it can serve as a new viable combinatorial target in lung cancers." (PMID 35229974, 2022). "Moreover, recent studies addressed the genomic alterations associated with distant metastases, e.g., ESR1 mutations and MYC, YAP1 amplifications enriched in metastatic breast cancer and lung cancer genomes, respectively." (PMID 33287735, 2020). "While lung cancer is not traditionally classified as hormone-dependent, ESR1 signaling has been implicated in tumor proliferation, survival, and metastasis through estrogen-mediated pathways, with overexpression correlating with poor prognosis in certain subtypes." (PMID 40573169, 2025). "However, data from pathology reports are used in routine clinical practice, and common mutations such as EGFR in lung cancer and ESR1 or PIK3CA mutations in breast or colon cancer are not present on the molecular board." (PMID 39457104, 2024).
lung carcinoma (continued). "In lung cancer, MALAT1 knockdowns alternatively splice the 5′ untranslated region of ESR1, the gene that codes for estrogen receptor α." (PMID 38095719, 2024). "It was shown that hypermethylation of ESR1 was detected only in lung tumors but not in adjacent normal lung tissue, suggesting that ESR1 hypermethylation may be associated with the development of lung cancer." (PMID 36726839, 2023). "A 2008 study observed that the use of real-time PCR to assess the methylation of the ESR1 promoter in the blood proved very useful for the diagnosis of lung cancer, as these methylated genes might become crucial biomarkers for the early detection of lung cancer." (PMID 35256890, 2022). "Interestingly, the novel G-protein-coupled estrogen receptor 1(GPER1), which is distinct from ER−α and ER−β because it can bind E2 with high affinity and transduces rapid nongenomic signaling, has also been shown to have higher expression levels in lung carcinoma than in normal lung tissues." (PMID 35664735, 2022). "ESR1 is overexpressed in NSCLC and promotes proliferation, migration, and invasion of lung cancer cells." (PMID 35924166, 2022). "In the present study, the survival analysis revealed that the major hubs including ESR1 and RELA were verified prognostic value on the overall survival of lung cancer." (PMID 33506873, 2021). "Analysis of these shortest path genes indicates that some of these genes, such as ESR1, FDXR, ABCA1, IRS1, HSP90AA1, FOXM1, and IGBP1 are related to lung cancer." (PMID 23762832, 2013). "The inclusion of ESR1 as a hub gene suggests that MQLEO may interfere with estrogen receptor signaling, potentially attenuating oncogenic pathways such as MAPK/ERK or PI3K/AKT, which are frequently dysregulated in lung cancer." (PMID 40573169, 2025). "It was clarified that the core components namely ismine, 5-hydroxy-7-methoxy-2-methylchromone, pluviine, and acetyllycoramine have multi-target mechanisms in mitigating lung cancer through the inhibition of AR, EGFR and ESR-1 proteins with involvement of 39 putative pathways." (PMID 39888361, 2025). "The mechanism of rhamnazin and ESR1 interaction in experimental models of lung cancer cells is not investigated in reported studies, which may be required for further profound functional validation." (PMID 36110188, 2022). "This phenomenon may not be limited to ESR1 FISH analysis, since similar artifacts were seen also in a case of EGFR-amplified lung cancer." (PMID 24367641, 2013). "However, this percentage could increase to 71.43%, considering that ESR1 (2.86%), ERBB4 (2.86%), and PIK3CA (8.57%) are not actionable genes in lung cancer." (PMID 39769478, 2024).
Insulin resistance (123 papers, 2007 to 2026). Increased resistance towards insulin, that is, diminished effectiveness of insulin in reducing blood glucose levels. "Mice with whole body deficiency of Esr1 develop insulin resistance, suggesting a protective role of Esr1 in insulin sensitivity." (PMID 40666843, 2025). "For instance, experimental evidence indicates that targeted deletion of the Esr1 gene encoding for ERα results in several abnormalities, including tissue inflammation and insulin resistance." (PMID 33923905, 2021). "The role of ESR1 in the development of insulin resistance has been described in human with a null mutation in the ESR1, leading to unresponsiveness to estrogen, who developed impaired glucose tolerance." (PMID 27191267, 2016). "The presence of G allele in ESR1 XbaI was associated with increased insulin resistance in HD patients and higher glucose levels in healthy women." (PMID 25077953, 2014). "The presence of the G allele in ESR1 XbaI was associated to increased insulin resistance in HD patients and higher glucose levels in healthy women." (PMID 25077953, 2014). "PvuII (rs2234693) and XbaI (rs9340799), mapped in intron 1, are the two most studied polymorphisms of ESR1 associated to CV risk factors, such as dyslipidemia, insulin resistance, hypertension, central obesity and type 2 diabetes." (PMID 25077953, 2014). "ESR1 was reduced in men with T2D and was linked to adiposity and insulin resistance." (PMID 39833659, 2025). "Many of the functional implications for ERs in modulating cardiometabolic risk have been discovered in rodents, where female mice with ESR1 mutations develop age-dependent vascular dysfunction and metabolic syndrome traits such as obesity, glucose intolerance, and insulin resistance." (PMID 36942499, 2023). "Insulin resistance is a complex pathophysiological feature with different organs and targets in the carbohydrate metabolism that can be genetically influenced; in this setting our study reinforces ESR1 Xbal polymorphism as a piece in insulin sensitivity." (PMID 25077953, 2014). "The ESR1 rs2234693 and rs9340799 polymorphisms have been reported as interfering with the action of the estrogen receptor, leading to the development of risk factors for cardiovascular disease, such as dyslipidemia, insulin resistance, hypertension, central obesity and type 2 diabetes." (PMID 23202974, 2012). "With respect to gene-trait assessment, expression of Esr1 in muscle is inversely correlated with the Homeostatic Model Assessment for Insulin Resistance (HOMA-IR) and body fat percent." (PMID 40328250, 2025). "Deletion of Esr1 from skeletal muscle produced insulin resistance, reduced myocellular oxidative metabolism, and disrupted metabolomic profiles." (PMID 40328250, 2025). "Since ARO and ESR1 gene expression in SAT were associated with markers of glycemia and insulin resistance, we explored their potential roles in regulating glucose uptake and lipid metabolism." (PMID 39833659, 2025). "Previous studies have shown that ESR1 deletion leads to increased adiposity, fibrosis, insulin resistance, and glucose intolerance in both male and female mice." (PMID 38932492, 2024). "Estradiol levels were lower andglucose blood levels and insulin resistance were higher in Sham operated (Sham) males compared to Sham females.Irs2, Pik3cd, and Esr1/2 mRNA levels were lower in the liver of Sham males than in Sham females." (PMID 33659826, 2020). "Resveratrol targets ESR1 gene and is being evaluated in the clinical trials in patients with insulin resistance and T2D." (PMID 33841528, 2020). "A previous study has shown that ESR1 and NOS3 predict postmenopausal CVD-related endothelial responses and can be used to predict insulin resistance and type 2 diabetes risk." (PMID 31752216, 2019). "Total body deletion of ESR1 as well as tissue-specific knockdown of ESR1 in male and female mice promotes increased adiposity, fibrosis, insulin resistance and glucose intolerance." (PMID 29196658, 2017).
Insulin resistance (continued). "Taken together, high ARO and altered ESR1:ESR2 balance in SAT in obese men may contribute to insulin resistance and T2D development." (PMID 39833659, 2025). "It was shown that whole-body deletion of ESR1 in mice affects multiple tissues resulting in hyperinsulinemia, insulin resistance, impaired oxidative metabolism, increased inflammation, impaired glucose tolerance and decreased physical activity as well as increased fat and body mass." (PMID 35203717, 2022). "Its role in development of insulin resistance has been demonstrated in ESR1 knockout mice." (PMID 26699868, 2015). "ESR1 XbaI and G894T NOS3 polymorphisms may be useful in accessing insulin resistance and type 2 diabetes risks, even before menopause and occurrence of metabolic disease." (PMID 25077953, 2014). "ESR1 XbaI and G894T NOS3 polymorphisms may be useful in accessing insulin resistance and type 2 diabetes risks in all women, even before menopause and occurrence of metabolic disease." (PMID 25077953, 2014). "Notably, our analysis revealed crucial hub targets such as EGFR, SRC, ESR1, MAPK1, and CASP3, alongside implicated signaling pathways, including those related to insulin resistance, the FoxO signaling pathway, the PPAR signaling pathway, and the IL-17 signaling pathway." (PMID 38845779, 2024). "ESR1 gene expression in SAT correlated negatively with adiposity and insulin resistance markers as well as with ARO expression, and tended to be lower in men with T2D." (PMID 39833659, 2025). "Estrogens are other well-known regulators of insulin resistance, and they enhance the expression of GLUT4 via activation of estrogen receptor 1 (ESR1)." (PMID 37106699, 2023). "But significantly lower plasma TC level is only seen in ESR1 variant carriers with AD diagnosis, which can be partially explained that low plasma TC levels could be a result of AD pathology and linked to increased insulin resistance especially in AD patients lack of estrogen protection." (PMID 30222591, 2018).
Infertility (122 papers, 2005 to 2026). "Other studies have also indicated that the knockout of the ESR1 gene is associated with infertility in females; in addition, the gene is also vital in the regulation of growth and expansion of the placental vascular network." (PMID 40723565, 2025). "For about 30 years, mice deficient in Esr1 have been to study the molecular mechanisms responsible for infertility, and to link them to various ovarian diseases." (PMID 38464972, 2024). "The disruption of the estrogen receptor 1 (Esr1) provokes infertility associated with a hemorrhagic, cystic phenotype similar to that seen in diseased or aged ovaries." (PMID 38464972, 2024). "PCOS is one of the most common causes of infertility in females and is characterized by metabolic alterations, which partially resemble the phenotype and characteristics of Esr1-deficient mice in regard to elevated serum E2 and LH levels." (PMID 37298232, 2023). "For example, specific mutations and polymorphisms in Esr1, the gene that encodes ERα, have been associated with greater body mass and adiposity, in addition to infertility in both sexes." (PMID 37425648, 2023). "ESR1 down-regulation is associated with the up-regulation of response to gonadotropins also in polycystic ovary syndrome, leading to infertility." (PMID 37505532, 2023). "Studies carried out so far in models using rats have shown that disruption of Esr1 causes infertility in both males and females." (PMID 36733805, 2022). "In ESR1 knock-out mouse males, this was associated with an increased frequency of damaged sperm membranes and abnormal sperm morphology linked to infertility." (PMID 31936899, 2020). "Some contradicting results of the role of ESR1 polymorphisms in spontaneous abortion or infertility were reported." (PMID 24228243, 2013). "These common ESR1 polymorphisms have been reported in relation with SA, infertility, successful IVF (in vitro fertilization), and preeclampsia." (PMID 24228243, 2013). "ESR1 rs9340799 was associated with EM-associated infertility and in vitro fertilization failure." (PMID 36968845, 2023). "Both male and female homozygous Esr1-deficient mice are infertile." (PMID 37298232, 2023). "Therefore, we speculated that depletion of Esr1, which leads to infertility, may be associated with imbalance in iron homeostasis." (PMID 38464972, 2024). "The infertility and hyperandrogenemic phenotype observed in adult α−/− males is very similar to that observed in male mice with global deletion of the gene encoding estrogen receptor alpha (Esr1), the estrogen receptor responsible for mediating the majority of estrogen's effects on the HPG axis." (PMID 28357399, 2017). "Some studies have also associated ESR1 and ESR2 gene polymorphisms with infertility and assisted reproduction outcomes." (PMID 38978624, 2024). "The most severe phenotype occurs when Esr1 is disrupted, resulting in infertility in both female and male mice, while depletion of Esr2 is associated with sub-fertility and comparatively normal gross morphology." (PMID 38464972, 2024). "In parallel, the deletion of Esr1 in glutamatergic neurons in females (Vglut2-ires-Cre;Esr1lox/lox) induced advanced puberty onset, disturbed cyclicity and infertility." (PMID 38978624, 2024). "As far as we know, this is the first study evaluating the association between FSHR rs6166 and ESR1 rs2234693 polymorphisms and PCOS in the Portuguese population with infertility." (PMID 37012960, 2023). "Most studies show that the eutopic endometrium of infertile patients with EMS exhibited notably higher ESR1/ERα levels during the secretory phase." (PMID 36979365, 2023).